WWOX (WW domain containing oxidoreductase)
Diseases named in the same sentence as WWOX in open-access papers (continued):
Sharing a sentence is not in itself a finding about the gene and the disease.
tumor (continued). "The tumor-suppressor gene, WW domain-containing oxidoreductase (WWOX), has been found to be lost in various types of cancers." (PMID 36364214, 2022). "WWOX protein has been demonstrated to be a tumor suppressor in many types of cancers, including HCC, due to its downregulated expression and functional links." (PMID 36530994, 2022). "WW-domain-containing oxidoreductase (WWOX) is generally considered as an untypical tumor suppressor." (PMID 36498839, 2022). "This concept also applies to WWOX, which was initially widely described as a tumor suppressor gene involved in multiple tumor types." (PMID 35573960, 2022). "There is growing evidence of the tumor suppressor activity of WWOX in a number of different cancers." (PMID 36271927, 2022). "The WW domain-containing oxidoreductase (WWOX) gene was originally discovered as a putative tumor suppressor spanning the common fragile site FRA16D, but as time has progressed the extent of its pleiotropic function has become apparent." (PMID 34831305, 2021). "WWOX and AP-2γ overexpression decreased tumor cell viability, proliferation potential, adhesion, clonogenicity and the ability to create spatial structures, but also increased apoptosis or migration rate." (PMID 33718178, 2021). "Our results also indicated that changes in WWOX expression influence the spatial growth of tumor cells." (PMID 33691672, 2021). "Briefly, when AP-2γ interacts with overexpressed WWOX, the individual biological processes supporting tumor development are inhibited (compared to K/C)." (PMID 33718178, 2021). "Immunohistochemistry studies have shown that WWOX protein levels can vary depending on tumor subtypes." (PMID 33946771, 2021). "The tumor suppressor activity of WWOX in a given cell type would therefore be dependent on the availability of one or more of its protein partners." (PMID 33946771, 2021). "To conclude, this research confirmed previous data regarding the tumor suppressor nature of WWOX and AP-2α, although the latter appeared to guide singular processes of G4 BLCA in an oncogene-resembling manner." (PMID 34204827, 2021). "When WWOX interacts with another tumor suppressor, the nature of its action permits for cooperation; however, when it coexists with an oncogene, there is greater necessity to oppose pro-cancerous actions." (PMID 33718178, 2021). "As a result, TMEM207 inhibits the various tumor suppressor function of WWOX, leading to the induction of ER stress-related apoptosis in cancer cells." (PMID 35047994, 2021). "The WW domain-containing oxidoreductase gene (WWOX) was cloned 21 years ago as a putative tumor suppressor gene mapping to chromosomal fragile site FRA16D." (PMID 33946771, 2021). "Over time, numerous studies support that WWOX exerts tumor suppressor effects through specific molecular actions that are mostly cell type specific." (PMID 34948746, 2021). "FRA16D CSF is known by association with genomic instability in different types of cancer, and WWOX downregulation is thought to play a role in tumor development." (PMID 34885058, 2021). "The localization of WWOX in this unstable chromosomal region was the first argument suggesting that it is a tumor suppressor gene." (PMID 33946771, 2021). "Ectopic expression of WWOX inhibits migration, tumor proliferation and metastasis of TNBC cell lines MDA-MB-231." (PMID 33946771, 2021). "Of note, WW domain containing oxidoreductase (WWOX) as tumor suppressor has been revealed to maintain mitochondrial respiration and attenuate Warburg effect by inhibiting HIF1-α and c-Jun by physical interaction with them." (PMID 34956899, 2021). "The WWOX gene is a tumor suppressor which can interact with a variety of transcription factors in inflammation and cancer." (PMID 34409086, 2021). "All of this work suggests that WWOX, due to its ability to interact with a large number of partners, exerts its tumor suppressive activity through a wide variety of molecular actions that are mostly cell specific." (PMID 33946771, 2021).
tumor (continued). "The WWOX protein has been shown to participate in a variety of cellular processes, such as DNA damage responses, cellular metabolism, and tumor suppression." (PMID 34948746, 2021). "The tumour-suppressor gene WWOX, located within the fragile site FRA16D in chromosome 16q23.3-24.1, is correlated to multiple cancers, especially breast, prostate, and ovary." (PMID 32784829, 2020). "In our previous study we reported that WWOX contributes to HNSCC tumor formation or progression as a result of genetic or epigenetic inactivations." (PMID 32368285, 2020). "Altogether, these findings underscore a significant role for WWOX in antagonizing metastasis, further highlighting its role and therapeutic potential in suppressing tumor progression." (PMID 32300104, 2020). "Initial evidence of the role of WWOX in tumor biology came from the discovery that the human WWOX gene resides in the genomic region FRA16D at 16q23, the second most common human chromosomal fragile site that is prone to frequent chromosome breakage." (PMID 33129329, 2020). "It is well established that WWOX expression is altered in many human malignancies and that WWOX functions as a tumor suppressor gene through dysregulation of target binding partners." (PMID 33129329, 2020). "Here, we report that WWOX restoration in highly metastatic MDA-MB435S cancer cells alters mRNA expression profiles; further, WWOX interacts with various proteins to exert its tumor suppressor function." (PMID 32300104, 2020). "WW domain-containing oxidoreductase (WWOX) has been initially known as a proapoptotic tumor suppressor." (PMID 33195192, 2020). "In contrast to our study, numerous studies have shown that WWOX directly influences cell viability and survival in normal and malignant epithelial cells in vitro and in vivo in mouse xenograft tumor models." (PMID 33129329, 2020). "In our previous study we observed significantly low level of WWOX gene expression in HNSCC tumor tissues." (PMID 32368285, 2020). "Human WWOX gene resides in the chromosomal common fragile site FRA16D and encodes a tumor suppressor WW domain-containing oxidoreductase." (PMID 32000863, 2020). "Based on the analysis of our previous studies, TMEM207 blocks the tumor suppressor function of WWOX through its PPxY motif." (PMID 31699801, 2019). "On the other hand, SETDB2 overexpression is associated with poor prognoses and tumour progression in gastric cancer through H3K9me3-mediated silencing of tumour suppressor genes WWOX and CADM1." (PMID 30850015, 2019). "WWOX is a tumor suppressor geneinvolved in the modulation of cancer-related pathways via protein–proteininteractions between the WW domains and various oncogenic proteins." (PMID 30356099, 2019). "We also provide the regulatory role of tumor suppressor WWOX in the upstream of TGF-β, Hyal-2, and Wnt signaling that cross talks with the Hippo pathway." (PMID 30805310, 2019). "The reduced expression of WW domain-containing oxidoreductase (WWOX) in many cancers which acts as a tumor suppressor, is related to aggressive properties and low prognosis." (PMID 31798348, 2019). "In the early stage of tumor progression, TGF-β acts as a tumor suppressor by inducing apoptosis and inhibiting tumor cell growth, due in part to its activation of the proapoptotic WWOX and Smad4." (PMID 31315632, 2019). "An interesting finding was that TMEM207 promotes tumor invasion, possibly through binding to a WWOX tumor suppressor molecule and impairing that molecule's tumor suppressive activity." (PMID 31699801, 2019).
tumor (continued). "The tumor suppressor function of WWOX was demonstrated by studies showing that its ectopic overexpression inhibited tumor growth." (PMID 30285739, 2018). "Recent advances highlight that a small transmembrane protein possessing a PPxY motif, called TMEM207, and its relatives are aberrantly expressed in various cancer cells and hinder the tumor suppressor function of WWOX through inhibiting its WW domain." (PMID 30214895, 2018). "In this report, we screened for new WWOX-interacting proteins to gain insight into the involvement of the WWOX tumor suppressor in breast cancer." (PMID 30285739, 2018). "Altogether, these data suggest that WWOX interactions are finely orchestrated to efficiently control the suppression of tumorigenic signaling pathways including DNA repair and tumor cell apoptosis." (PMID 30285739, 2018). "In mammalian cells, WWOX ablation is inversely correlated with increased levels and activity of hypoxia-inducible factor 1α (HIF1α-enhancing cell transformation and tumor growth." (PMID 29724996, 2018). "WWOX has been shown to act as a tumor suppressor modulating cellular metabolism via regulating hypoxia-inducible factor 1α (HIF-1α) levels and function." (PMID 29724996, 2018). "Although the compelling evidence that indicates with no doubt that WWOX is a tumor suppressor gene, the presence of WWOX in a fragile locus in the genome raises suspicion about its identity of being a classical tumor suppressor gene." (PMID 30619734, 2018). "The WW domain‐containing oxidoreductase (WWOX) functions as a tumour suppressor in oral carcinogenesis." (PMID 29164763, 2018). "The most frequently expressed and best-characterized CFSs in the human genome are FRA3B and FRA16D, which harbour the tumour suppressor genes FHIT and WWOX, respectively." (PMID 29695617, 2018). "The expression of WWOX gene in OC induces apoptosis and inhibits cell proliferation both in differentiated tumor cells and in cancer stem cells (CSCs)." (PMID 29966369, 2018). "In conclusion, our study reveals WWOX as a tumor suppressor with critical roles in HCC suppression through maintaining moderate glucose metabolism and inhibiting uncontrolled cell proliferation." (PMID 29724996, 2018). "TMEM207 plays a role in the progression of gastric signet‐ring cell carcinoma by binding to WWOX and abrogating its tumour suppressor function." (PMID 29164763, 2018). "A decrease in the expression of WWOX was found when compared to adjacent tumor‐free tissues, which led to worse overall survival (OS) and recurrence‐free survival (RFS) and, therefore, was considered as an independent negative factor in the prognosis of HCC." (PMID 29905011, 2018). "TMEM207 competes with WWOX-interacting oncogenic molecules for binding to the WW domain of WWOX, thereby inhibiting the tumor suppressor function of WWOX." (PMID 30214895, 2018). "Recent advances demonstrate that several cancer cell types gain ectopic overexpression of TMEM207 during carcinogenesis, and then abolish the tumor suppressor function of WWOX through competitively binding with its WW domain." (PMID 30214895, 2018). "WW domain‐containing oxidoreductase (WWOX), which has a protein‐interaction domain and is regarded to be a tumor suppressor, has been known to play an important role in anti‐angiogenesis and cancer progression." (PMID 29905011, 2018).
tumor (continued). "In this review, we have summarized the recent findings of pathobiological protein networks that abolish the tumor suppressor function of WWOX in cancer cells, especially focusing on a small transmembrane protein, TMEM207." (PMID 30214895, 2018). "A small transmembrane protein, TMEM207, appears to be aberrantly expressed and blocks the tumor suppressor function of WWOX through its PPxY motif." (PMID 30214895, 2018). "It is believed that the tumor suppressor function of WWOX is impaired by various molecular events in cancer cells." (PMID 30214895, 2018). "A very interesting aspect of WWOX tumor suppressive function is changing the signaling pathway of different proteins to achieve the same outcome." (PMID 30619734, 2018). "When WBP2 binds with WWOX, a tumor suppressor, ER transactivation and tumor growth can be suppressed." (PMID 28724435, 2017). "In a non-canonical signaling, TGF-β binds membrane hyaluronidase Hyal-2 for recruiting tumor suppressors WWOX and Smad4, and the resulting Hyal-2/WWOX/Smad4 complex is accumulated in the nucleus to enhance SMAD-promoter dependent transcriptional activity." (PMID 27845895, 2017). "WW domain-containing oxidoreductase (WWOX), which is encoded by the chromosomal fragile site spanning gene, is a tumor suppressor in several human cancers." (PMID 28977834, 2017). "In a non-canonical pathway, transforming growth factor beta (TGF-β) binds membrane Hyal-2 and then recruits tumor suppressors WWOX and Smad4, and the resulting Hyal-2/WWOX/Smad4 induces SMAD-dependent transcriptional activation in the nucleus." (PMID 27845895, 2017). "The expression level of WWOX and the methylation of the promoter are inversely correlated: 10 different alterations in the coding sequences and 18 different alterations in the non-coding sequences of the WWOX gene in HNSCC tumor samples are reported." (PMID 28045433, 2017). "In our results, we found that evodiamine induced cell arrest, and it is known that the activation of WWOX induces cell arrest to exert an anti-tumor activity." (PMID 28708106, 2017). "WWOX has been previously reported as a tumor suppressor in a diverse array of cellular activities, including growth, proliferation, apoptosis, and tumor suppression, leading to dysregulation of multiple oncogenes and tumor suppressors." (PMID 28724435, 2017). "Human WW domain-containing oxidoreductase (WWOX) gene has been identified as a tumor suppressor gene in multiple cancers." (PMID 28426730, 2017). "WWOX was mapped to this region, and the loss of function of WWOX in cancer cells was associated with mucinous histologies and a poor prognosis, suggesting that WWOX suppresses tumor progression." (PMID 27655721, 2016). "An additional integrated in silico analysis confirmed that rs11545028 affects WWOX expression, which significantly correlates with tumor expression and subsequently with tumor development and aggressiveness." (PMID 27655721, 2016). "Human WW domain-containing oxidoreductase (WWOX) is a tumor suppressor that has been reported to lose function due to genetic alterations carcinogenesis." (PMID 26910372, 2016). "In this study, the deletion genotypes of CNV-67048 have lower WWOX mRNA levels in both tumor tissues and their borderline normal tissues, compared with the no deletion genotype." (PMID 26910372, 2016). "The deletion genotypes of CNV-67048 have lower WWOX mRNA levels in both tumor tissues (P = 0.001) and border tissues (P = 0.002)." (PMID 26910372, 2016). "Like FHIT, WWOX has a range of tumor-suppressing functions, affecting DNA repair and apoptosis, which identifies it as a master regulator that protects cells against genomic instability and tumor progression." (PMID 27977694, 2016).
tumor (continued). "In a non-canonical pathway, binding of TGF-β to HYAL-2 results in recruitment of tumor suppressors WWOX and SMAD4 and their relocation into the nucleus." (PMID 27999774, 2016). "WWOX also participates in the cellular metabolism and affects tumor metabolism and thus inhibits tumorigenesis." (PMID 27190995, 2016). "The WWOX protein is a kind of broad-spectrum tumor suppressor involving many kinds of human cancers." (PMID 27190995, 2016). "Together these results provide a molecular basis for the tumor suppressor functions of WWOX and the better prognosis observed in cancer patients with higher levels of WWOX activity." (PMID 26302329, 2015). "Here we discuss supporting evidence favoring active and tumor suppressor functions of WWOX in tumorigenesis." (PMID 27551470, 2015). "Role of tumor suppressor WWOX in metastasis is poorly explored, though some studies suggested a potential role." (PMID 26256646, 2015). "Accordingly, emerging findings demonstrate that WWOX protein has pleiotropic tumor-suppressive functions, particularly by regulating the DNA DDR." (PMID 27551470, 2015). "One such example of a tumor suppressor gene is the WW domain-containing oxidoreductase (WWOX), which spans the CFS FRA16D." (PMID 27551470, 2015). "Our results show that WWOX expression is down-regulated especially in advanced-stage tumor samples or in tumors with SCC." (PMID 25612104, 2015). "WWOX is among the most significantly deleted genes in cancers, suggesting a selective pressure because of a tumor suppressor activity and also because of the fragility of that locus." (PMID 27551470, 2015). "Conversely, ectopically expressed WWOX has been shown to function as a suppressor of tumor growth since restoration of WWOX activity in cancer cells inhibits their growth in vivo." (PMID 26302329, 2015). "In conclusion our findings indicate that WWOX overexpression is accompanied by the downregulation of genes that are involved in tumor cell migration and invasion rendering them less metastatic and less aggressive." (PMID 26256646, 2015). "Further delineation of WWOX tumor suppressor functions and other products of CFSs, both in vitro and using animal models, should contribute to better understanding of carcinogenesis." (PMID 27551470, 2015). "We detected the WWOX transcript in both tumor and normal tissue samples except for one tumor tissue." (PMID 25612104, 2015). "Several lines of evidence have indicated that the WW domain-containing oxidoreductase (WWOX) acts as a tumor suppressor (reviewed in8, 9, 10)." (PMID 26256646, 2015). "In our study group we observed 10 different alterations in the coding sequences and 18 different alterations in the non-coding sequences of the WWOX gene in HNSCC tumor samples." (PMID 25612104, 2015). "Alterations of the WWOX gene at the genomic and expression levels have been reported in numerous neoplasias including breast, ovarian, esophageal, gastric, pancreas, lung or oral cancers and multiple myeloma." (PMID 25612104, 2015). "The notion that spontaneous tumor formation in WWOX +/− mice needs further investigation, since the wild type mice tend to spontaneously grow tumors." (PMID 25686832, 2015). "At the molecular level, we found that miR-153 inhibited protein level of WWOX, a tumor suppressor and inhibitor of β-catenin signaling, through targeting its 3′-untranslated region." (PMID 25708809, 2015). "Altogether, these data suggest that WWOX is playing a critical role in OS development and functions as a tumor suppressor." (PMID 26256646, 2015). "A known tumor suppressor gene, WWOX resides with the second most common fragile site in the human genome." (PMID 24663488, 2014).